FDX1 (ferredoxin 1)
Diseases named in the same sentence as FDX1 in open-access papers (continued):
Sharing a sentence is not in itself a finding about the gene and the disease.
glioma (continued). "Through the analysis of data from CGGA and TCGA, we found a positive correlation between FDX1 expression and glioma grade." (PMID 36523779, 2022). "This study aimed to explore the relationship and possible signaling pathways between FDX1 expression and the prognosis of glioma patients utilizing bioinformatics." (PMID 36523779, 2022). "To further understand the relationship between the expression of FDX1 gene and the clinical characteristics of glioma patients, we performed univariate and multivariate regression analysis." (PMID 36523779, 2022). "To further explore the role of FDX1 in gliomas, we attempted to identify potential Cuproptosis key genes by bioinformatics analysis, comparing the co-expression gene of FDX1 in gliomas with with an additional 6 lipoacylation-related genes." (PMID 36523779, 2022). "To further verify our analysis results, we detected the expression of FDX1 in glioma tissues and cell lines." (PMID 36523779, 2022). "To further explore the relationship between Cuproptosis and autophagy, we analyzed the correlation between the molecular markers of the Cuproptosis process represented by FDX1 and the key genes of autophagy in glioma by co-expression network analysis." (PMID 36523779, 2022). "The prognosis-related independent risk factors FDX1 and CDKN2A identified from CARSs are considered potential prognostic biomarkers for WHO 2/3 glioma." (PMID 36059638, 2022). "The results showed that FDX1 protein was expressed in the glioma cell line U251 cells, and was mainly expressed in the cytoplasm and cell membrane." (PMID 36523779, 2022). "It is worth noting that the expression of the FDX1 gene was abnormally high in glioma than normal tissues, especially in glioblastoma (GBM), the expression level was the highest." (PMID 36523779, 2022). "To further explore the function of FDX1 in glioma, we used the LinkedOmics database to analyze the gene co-expression network centered on FDX1 in glioma." (PMID 36523779, 2022). "Further, we separately analyzed the correlation between FDX1 expression and prognosis in all glioma patients, LGG and GBM patients." (PMID 36523779, 2022). "Further, we performed gene annotation on the co-expressed genes of FDX1 in glioma, GO annotation, and KEGG signaling pathway enrichment analysis showed that FDX1 expression is closely related to immune response and inflammation." (PMID 36523779, 2022). "The possible biological processes and functions of FDX1-related in glioma were annotated through gene enrichment." (PMID 36523779, 2022). "Previous studies have shown that FDX1 is highly expressed in glioma, where its primary function involves regulating the lipidation of tumor proteins and copper metabolism, significantly impacting the clinical prognosis of glioma patients." (PMID 41463095, 2025). "Costaining revealed elevated GFAP+-SLC31A1+, GFAP+-FDX1+, GFAP+-DLAT+, and GFAP+-DLST+ astrocytes in DSF-treated ECM mice, consistent with reports linking copper overload (e.g., via FDX1/SLC31A1 upregulation) to glioma progression and copper/zinc ionophores (e.g., CPT/ZPT) to astrocyte toxicity." (PMID 41214704, 2025). "Studies have found that the copper death-related gene FDX1 is abnormally expressed in glioma tissues, suggesting that copper metabolism imbalance may be involved in glioma progression." (PMID 41463095, 2025). "FDX1 knockdown notably hindered aerobic glycolysis and glioma cell proliferation." (PMID 38918694, 2024). "Methylation of FDX1 is believed to promote malignant behavior in glioma." (PMID 39184045, 2024). "Contrarily, in glioma, FDX1 expression levels were upregulated compared with normal tissues." (PMID 38918694, 2024). "Although FDX1 may play a pivotal position in immunotherapy for many cancers, reports regarding its function in gliomas are limited." (PMID 37301546, 2023). "We additionally determined the expression of FDX1; the findings suggested that FDX1 could promote the invasion and migration ability of glioma cells in vitro." (PMID 37301546, 2023).
glioma (continued). "Additionally, transwell and cell scratch assays demonstrated that FDX1 knockdown significantly attenuated the migration ability of glioma cells." (PMID 37515314, 2023). "For OS outcomes of glioma patients, a 9-gene signature was selected to construct the prognostic score using their regression coefficients: Riskscore = (0.8949)*FDX1 + (0.4902)*DLD + (0.0778)*DLAT + (-0.9324)*LIAS + (0.1132)*GLS + (0.903)*LIPT1 + (-0.1847)*MTF1 + (-0.2352)*PDHA1 + (-0.2045)*PDHB." (PMID 36915038, 2023). "In this study, we used the miRNA microarrays datasets GSE61710 to analyze DEmiRNAs in normal brain tissue versus glioma tissues searching for targets that regulate CRGs, and found that hsa-miR-606 abnormally expressed in glioma has a binding site with FDX1 mRNA." (PMID 36915038, 2023). "Moreover, to demonstrate the specific role of cuproptosis in gliomas, we selected FDX1, a key regulator of cuproptosis, for cellular experiments." (PMID 37515314, 2023). "We investigated the correlation between FDX1 and clinicopathological parameters of glioma." (PMID 37301546, 2023). "The findings also indicated that FDX1 may serve as a survival indicator and potential therapeutic target in gliomas." (PMID 37301546, 2023). "Our study found that FDX1 levels were highly elevated in glioma tissue." (PMID 37301546, 2023). "FDX1 silencing-induced inhibitions of cell invasion and migration were found to be associated with inactivation of the NOD-like receptor signaling pathway in glioma." (PMID 37301546, 2023). "In this study, we found that FDX1 plays an important role in the migration of glioma cells and invasion of the immune microenvironment; this could be become a new prognostic and immune-related biomarker." (PMID 37301546, 2023). "We also constructed FDX1-knockdown glioma cell lines (U87 and U251)." (PMID 37301546, 2023). "Therefore, we further verify the tumor-promoting role of FDX1 in LGG according to Chinese Glioma Genome Atlas (CGGA) database." (PMID 36825202, 2023). "FDX1 promoted glioma cell proliferation and migration, possibly through the PI3K/AKT/mTOR pathway." (PMID 37515314, 2023). "Our findings further confirmed that FDX1 may promote the progression of gliomas by regulating PD-L1 expression via NOD-like receptor signaling pathway activation." (PMID 37301546, 2023). "We further confirmed the correlation of FDX1 with glioma immune infiltration and proposed that FDX1 may serve as a novel immunotherapy biomarker." (PMID 36523779, 2022). "The FDX1 level was independently prognostic; targeting of FDX1 expression might serve as a cuproptosis-specific therapeutic strategy for glioma prevention and treatment." (PMID 36579333, 2022). "Notably, FDX1 has been found to be highly expressed in gliomas and is primarily involved in lipid acylation of tumor proteins and cuproptosis, which significantly affects the prognosis of low-grade gliomas." (PMID 39184045, 2024). "In conclusion, FDX1 may play an important role in the diagnosis and treatment of gliomas." (PMID 37301546, 2023). "Furthermore, Cox regression analysis in the TCGA database showed that FDX1, LIPT1, DLD, DLAT, SLC31A1, ATP7A, and DLST might be risk factors; however, LIAS, ATP7B, and GCSH were significant preventive factors for gliomas." (PMID 37515314, 2023). "Further analysis of the relationship between CRGs and the prognosis of gliomas revealed that high expression of FDX1, DLD, DLAT, and LIPT1 was associated with poorer survival in glioma patients, and high expression of CDKN2A and PDHA1 was significantly associated with better survival in gliomas." (PMID 36915038, 2023). "The protein of FDX1 was mainly localized to the mitochondria and was enhanced in cell lines of A-431 (human epidermoid carcinoma cells), U-2 OS (human osteosarcoma cells), U-251 MG (human glioma cells), and particularly in CACO-2 (human colorectal adenocarcinoma cells)." (PMID 36210836, 2022).
glioma (continued). "In summary, FDX1 may serve as a potential immunotherapy target and prognostic marker for Glioma." (PMID 36523779, 2022). "Any prognostic utility of glioma FDX1 status remains unclear." (PMID 36579333, 2022). "In addition, we found that FDX1 status was important in terms of glioma progression." (PMID 36579333, 2022). "However, the specific biological function of FDX1 in glioma is currently unclear." (PMID 36523779, 2022). "However, the role and biological function of FDX1 in gliomas are currently unclear." (PMID 36523779, 2022). "Notably, the methylation modification of FDX1 may drive the malignant progression of glioma." (PMID 41463095, 2025). "In glioma cells, C-MYC inhibits mitophagy by upregulating FDX1 expression and suppressing the expression of the autophagy marker protein LC3." (PMID 41463095, 2025). "Mechanistic studies have revealed that cellular myelocytomatosis viral oncogene homolog (C-MYC), as a key regulator, strongly enhances glioma cell growth and spread via the YTH domain-containing family protein 1 (YTHDF1)-regulated FDX1 methylation mechanism." (PMID 41463095, 2025). "In gliomas, EREG expression is closely correlated with the expression of the checkpoint protein PD-L1 and inversely correlated with the expression of FDX1, which is related to cuproptosis." (PMID 39062119, 2024). "Functional experiments further revealed that the target gene C-MYC enhances the proliferation and invasion of glioma cells through YTHDF1 and FDX1 methylation, possibly due to aberrant copper ion behavior in mitochondria." (PMID 39184045, 2024). "Since the HR values of FDX1, SUMF1, SLC31A1 were the highest in the seven‐gene signature, we were going to validate their protein expression in human glioma specimens." (PMID 36856182, 2023). "The expression levels of FDX1 and LIPT1 varied in different histological grades of glioma, as the glioma grade was increased, there was an upward trend of FDX1 and LIPT1 expression." (PMID 36915038, 2023). "We performed KEGG enrichment analysis to explore the mechanism of FDX1-mediated regulation in glioma progression; we found that the NOD-like receptor signaling pathway was positively enriched in the high FDX1 expression group." (PMID 37301546, 2023). "The expression of GLS (p < 0.001), LIPT1, FDX1, SLC31A1 (p < 0.01), DLST, CDKN2A, PDHA1, ATP7A, ATP7B, and NFE2L2 (p < 0.05) was different between glioma and adjacent tissues." (PMID 36936439, 2023). "The results showed that the transcripts level of FDX1 in GBM and Low grade glioma (LGG) was significantly higher than normal tissues." (PMID 36523779, 2022). "By exploring the relationship between the FDX1 gene and immune checkpoint genes, we found that there is a strong co-expression relationship between the FDX1 gene and immune checkpoint Suppressor gene TGFB1 in glioma." (PMID 36523779, 2022). "Thus, FDX1 may regulate immune infiltration into the glioma microenvironment." (PMID 36579333, 2022). "In glioma patients, the levels of CDKN2A, FDX1, DLD, DLAT, LIAS, LIPT1, and PDHA1 were significantly associated with the OS, disease-specific survival, and progression-free interval." (PMID 36579333, 2022). "We found that FDX1 status is strongly correlated with glioma prognosis, the WHO glioma grade, IDH status, and 1p19q co-deletion status." (PMID 36579333, 2022). "The results showed that the protein expression of FDX1 in Normal glial cell (NHA cell) and glioma cell lines (U87-MG, U251, U373, and A172) was significantly up-regulated compared with the normal group." (PMID 36523779, 2022). "We found that both FDX1 and CDKN2A were highly expressed in WHO 2/3 glioma tissue samples compared to normal brain tissue by immunohistochemistry." (PMID 36059638, 2022). "In order to further prove our conclusion, we also detected the mRNA expression of FDX1 gene in NHA cell and glioma cell lines." (PMID 36523779, 2022).
glioma (continued). "The results showed that the protein expression of FDX1 in grade II, III, and GBM of glioma was significantly up-regulated compared with the normal group." (PMID 36523779, 2022). "Furthermore, cuproptosis-related genes (LIPT1, FDX1, and DLAT) have emerged as therapeutic targets in epilepsy and gliomas, underscoring its broad relevance." (PMID 41214704, 2025). "We further confirmed the abnormal expression of FDX1, SUMF1, and SLC31A1 proteins in glioma samples by immunohistochemistry, and the correlation between high expression of FDX1 protein and poor prognosis in glioma patients." (PMID 36856182, 2023). "Patients with glioma had a poor prognosis irrespective of high- or low-FDX1 expression; this was probably related to the smaller sample size or the individual clinical parameters." (PMID 37301546, 2023). "We verified the correlation among FDX1, SLC31A1, and macrophage infiltration in 56 glioma tissues." (PMID 37515314, 2023). "In addition, by analyzing TCGA cohort mRNA expression data, we also found that FDX1 and CDKN2A were upregulated in WHO 2/3 glioma tissues." (PMID 36059638, 2022). "The results showed that FDX1 expression was associated with overall survival (OS) and progression-free survival (PFS) in patients with low-grade glioma, but not with OS or PFS in GBM patients." (PMID 36523779, 2022). "We performed receiver operating characteristic curve (ROC) analyses to assess whether various CRG levels aided glioma detection; the areas under the curves (AUCs) were >0.9 for CDKN2A, FDX1, DLD, and PDHB." (PMID 36579333, 2022). "Studies have demonstrated that c-MYC can upregulate FDX1 via YTHDF1 with increased sensitivity to cuproptosis in glioma cells and that copper stress promotes METTL16 lactylation, leading to elevated METTL16 expression, which positively mediates cuproptosis through the m6A modification of FDX1 mRNA." (PMID 41373022, 2025). "Immunohistochemically, FDX1 staining was positive in gliomas but negative in normal tissues." (PMID 36579333, 2022).
clear cell renal cell carcinoma (22 papers, 2022 to 2026). "Overexpression of ferredoxin 1 (FDX1) is associated with improved survival in clear-cell renal carcinoma." (PMID 41424843, 2026). "In renal clear cell carcinoma, reduced FDX1 expression is associated with disease progression, poor prognosis, and dysregulation of immune cell infiltration." (PMID 40276654, 2025). "Association of ferredoxin 1 (FDX1) expression with clinicopathological characteristics in patients with clear cell renal cell carcinoma." (PMID 36225932, 2022). "In another study, FDX1 was significantly associated with immune infiltration levels and programmed cell death protein 1 (PD-1) expression in clear cell renal cell carcinoma." (PMID 36263125, 2022). "ADM enhances resistance to sunitinib in clear cell renal cell carcinoma by downregulating FDX1 expression and inhibiting cuproptosis." (PMID 40074697, 2025). "It has been reported that high expression of FDX1 indicates a good prognosis in Clear cell renal cell carcinoma." (PMID 36173462, 2023). "There was a significant positive correlation between FDX1 expression and OS in patients with clear-cell renal-cell carcinoma." (PMID 37763758, 2023). "An experiment in vitro showed FDX1 is downregulated by elesclomol, resulting in inhibiting cell viability of bladder cancer, clear cell renal cell carcinoma, and prostate cancer cells." (PMID 36210836, 2022). "Clear cell renal cell carcinoma (ccRCC) is an aggressive cancer characterised by metabolic reprogramming, and FDX1 is a critical regulator of cuproptosis." (PMID 36186457, 2022). "Additionally, FDX1, a gene related to fatty acid metabolism, has been shown to regulate the progression of clear-cell renal carcinoma by influencing the immune microenvironment of tumor cells." (PMID 37796199, 2023). "Moreover, we investigated the biological function of FDX1 in tumors using single-cell database and enrichment analysis and verified in vitro experiments with bladder cancer, clear cell renal cell carcinoma, and prostate cancer cell lines." (PMID 36210836, 2022). "However, further research is needed to determine how the cuproptosis-related gene ferredoxin 1 (FDX1) affects the tumor immune response and its prognostic significance in clear cell renal cell carcinoma (ccRCC)." (PMID 36225932, 2022). "However, it is unclear whether FDX1 has prognostic and immunotherapeutic value for clear cell renal carcinoma (ccRCC)." (PMID 37432054, 2023). "Here, ferredoxin-1 (FDX1), a mitochondrial Fe-S protein frequently downregulated in clear cell renal cell carcinoma (ccRCC), is identified as a dual regulator of ferroptosis and antitumor immunity." (PMID 41199656, 2025). "However, the effect of FDX1 expression on clear renal cell carcinoma (ccRCC) is unknown." (PMID 36105937, 2022).